TET2 (tet methylcytosine dioxygenase 2)
Diseases named in the same sentence as TET2 in open-access papers (continued):
Sharing a sentence is not in itself a finding about the gene and the disease.
anemia (13 papers, 2015 to 2025). A reduction in the number of red blood cells, the amount of hemoglobin, and/or the volume of packed red blood cells. "We have previously shown that tet2-mutant fish develop trilineage dysplasia by 15 months of age, which progresses over the next 7 months to anemia, thus fulfilling the diagnostic criteria of MDS." (PMID 37937078, 2023). "Compared to Tet2-mutant mice, the co-mutant Tet2/Stag2 mice exhibit more severe phenotypes, including leukocytosis, anemia, and thrombocytopenia." (PMID 40563403, 2025). "We and others have shown an erythroid maturation defect in the bone marrow of Tet2–/–/Flt3ITD AML mice leading to anemia." (PMID 38950330, 2024). "Collectively, these results support a model in which increased iron uptake and TET2 expression in splenic HSCs during anemia promote DNA demethylation and enhanced erythropoiesis." (PMID 38225226, 2024). "This study shows that iron instructs erythroid differentiation of HSCs during anemia in a Tet2-dependent manner." (PMID 38225226, 2024). "Overall, our results provide insight into the instructive role of iron in promoting TET2-mediated DNA demethylation and erythropoiesis in splenic HSCs during anemia." (PMID 38225226, 2024). "Here, we show that iron is increasingly taken up by HSCs during anemia and induces erythroid gene expression and regeneration in a Tet2-dependent manner." (PMID 38225226, 2024). "By 24 months of age, each of the tet2-mutant fish developed anemia, which, together with the marked dysplasia of the developing hematopoietic progenitors in the kidney marrow, formed the basis for an MDS diagnosis." (PMID 37937078, 2023). "In a Tet2-deficient mouse HSPC transplant model, we found cGAS inhibition restored hemoglobin production, resolved anemia, and suppressed monocyte production." (PMID 35788117, 2022). "In contrast to Tet2-only mutant mice, Tet2/Stag2-mutant mice developed leukocytosis, absolute monocytosis, anemia, and thrombocytopenia." (PMID 33351783, 2021). "Double mutant mice generated by the breeding of Sf3b1+/K700E and Tet2 knock-out mice manifested a more severe anemia compared to mice with a sole alteration in Sf3b1 or Tet2." (PMID 31766606, 2019). "As expected from our examination of peripheral blood, Tet2/3 DKO mice developed profound anaemia and lymphopenia." (PMID 26607761, 2015). "While we show that calpains might be involved in destabilizing TET2 protein in HSPCs, whether the inhibition of this mechanism is responsible for TET2 stabilization in HSCs during anemia remains to be seen." (PMID 38225226, 2024). "Furthermore, by 24 months of age, most of the tet2 homozygous mutant fish tested were found to have anemia." (PMID 37937078, 2023). "Mechanistically, caspase-1 degraded the master erythroid transcription factor, GATA binding protein 1, provoking anemia and myeloid lineage bias that was reversed by cGAS inhibition in vitro and in Tet2–/– hematopoietic stem and progenitor cell–transplanted mice." (PMID 35788117, 2022). "We recently described a zebrafish model of MDS in which both tet2−/− and tet2+/− fish develop trilineage dysplasia at 11 months of age and full-blown MDS with anemia by 24 months." (PMID 31064769, 2019). "The number of HSCs in the spleen, but not bone marrow, increases upon anemia and these HSCs exhibit enhanced proliferation, erythroid differentiation, iron uptake, and TET2 protein expression." (PMID 38225226, 2024).
endometrial cancer (13 papers, 2015 to 2025). Primary or metastatic malignant neoplasm involving the endometrium (mucous membrane that lines the endometrial cavity). "There is considerable data reporting TET2 mutation/loss and association with survival in female‐associated cancers, such as breast, ovarian, cervical, and endometrial cancers." (PMID 40116537, 2025). "Zhang and colleagues reported that complete loss of TET2 protein in endometrial carcinoma was significantly associated with shorter OS (46.74 months) compared to TET2‐positive cases (66.57 months) (HR [95% CI] = 24.189 [3.115–187.822], p < 0.01)." (PMID 40116537, 2025). "In contrast, TET2+/5hmC+ endometrial cancer was significantly associated with well-differentiated cells, minimal myometrial invasion, negative lymph node metastasis, and lower tumour stage." (PMID 39336751, 2024). "Moreover, in accordance with our results, we hypothesise that ARCH-related mutations (in the DNMT3A and TET2 genes) could be associated with a worse prognosis for endometrial cancer patients." (PMID 37175518, 2023). "In another study, we compared the differential level of TET2 between normal endometrial tissue and endometrial cancer tissue was observed using the endometrial cancer data in TCGA database." (PMID 38515066, 2024). "Aberrant DNA methylation is a vital molecular alteration commonly detected in type I endometrial cancers (EC), and tet methylcytosine dioxygenase 2 (TET2) and 5-hydroxymethylcytosine (5hmC) play significant roles in DNA demethylation." (PMID 38515066, 2024). "The differential expression of TET2 between normal endometrial tissue and endometrial cancer tissue was observed using the endometrial cancer data in TCGA database." (PMID 35480097, 2022). "For example, a higher level of TET3 and lower levels of TET1 and TET2 were found in endometrial cancer compared with the normal endometrium, whereas endometrial cancer tissues showed lower levels of global hydroxymethylation at the same time." (PMID 36685517, 2022). "In this study, we detected the expressions of TET2 and 5hmC and analyzed their clinical significance in endometrial adenocarcinoma to explore the possible mechanism of TET2 in the development of endometrial cancer." (PMID 35480097, 2022). "TET2 expression has been shown to be significantly reduced in severe endometrial cancer and cervical squamous cell carcinoma tissues compared to their normal counterparts." (PMID 35372016, 2022). "The clinical significance of TET2 expression in endometrial carcinoma was analyzed from TCGA public database." (PMID 35480097, 2022). "We analyzed TET2 expression in a series of 88 endometrial carcinoma samples and 20 normal proliferative endometrium samples via immunohistochemistry." (PMID 35480097, 2022). "TET2 expression was significantly reduced in high-grade, advanced, and recurrent endometrial carcinoma from TCGA database." (PMID 35480097, 2022). "Multivariate analysis further demonstrated that the TET2/5hmC relationship could be an independent prognostic factor for endometrial cancer (HR: 2.84, 95% confidence interval [CI] 1.23–3.61, p = 0.007)." (PMID 39336751, 2024). "Metformin is known to be an AMPK activator, so could metformin inhibit the proliferation of endometrial cancer by regulating TET2?" (PMID 35480097, 2022). "Further studies are needed to fine tune the mechanisms by which TET2 might be deregulated in endometrial cancer." (PMID 35372016, 2022). "Moreover, lower TET1 and TET2 expression has been reported in the cases of endometrial cancer." (PMID 37576599, 2023). "Thus, the role of TET3 in endometrial cancer seems to be different than TET1 or TET2, and this protein may be involved in modifications of histones by targeting other proteins to chromatin." (PMID 34948036, 2021). "Our previous studies showed that TET1 and TET2 messenger RNA expression was lower and TET3 expression was higher in endometrial cancers compared to normal tissues." (PMID 34948036, 2021).
endometrial cancer (continued). "We thus propose that future studies on the role of additional multi-cancer regions, such as 1q32/MDM4, 4q24/TET2, 8q24, 10p12/MLT10, 14q24/RAD51B8 or 19q13/MERIT40, are worthwhile endeavours for cancers that are relatively understudied, including endometrial cancer." (PMID 25487306, 2015).
viral infection (13 papers, 2018 to 2025). "After acute viral infection in mice with selective Tet2 loss in CD8+ T cells, a memory phenotype dependent on cell-intrinsic mechanisms rather than the disruption of antigen-driven cell expansion or effector function is preferentially adopted." (PMID 34222235, 2021). "Susceptibility to predominantly viral infections was observed in TET2, TPP2 and TNFAIP3 patients while chronic mucocutaneous candidiasis (CMC) and mendelian susceptibility to mycobacterial disease (MSMD) were characteristic of STAT1 GOF and IL12RB1 patients, respectively." (PMID 34447369, 2021). "TET2 is a DNA dioxygenase that demethylates the IFITM3 promoter during viral infection, inhibiting HIV Env trafficking and reducing viral spread." (PMID 38951492, 2024). "For instance, mouse models that lack specifically TET2 in T cells exhibit defects in immune response against viral infection." (PMID 35990681, 2022). "After viral infection, mice deficient in CXXC5 or – to a lesser extent – in Tet2 fail to show an early IFN response, and the related production of IFNα/β, CCL-5, tumor necrosis factor (TNF), and IL-12 is attenuated." (PMID 34222235, 2021). "CD8+ T cells with Tet2 conditional KO exhibit full effector functional role upon acute viral infection, and Tet2 deletion enhances memory CD8+ T-cell formation." (PMID 33184433, 2020). "TET genes, particularly TET2, play an antagonistic role by restraining inflammatory GE in macrophages and its level was shown to decrease after viral infection." (PMID 30065722, 2018). "Cells under inflammatory stress are expected to produce poor-quality results, especially under stressors such as viral infection and CHIP (typically caused by clones carrying mutations in epigenetic regulators like TET2, DNMT3A and ASXL1), contributing to a lower fraction of high-quality reads." (PMID 37372428, 2023). "Considering the important role of type I interferons in the host response to viral infection, these data suggest Tet2 might play a role herein." (PMID 35011643, 2021). "Moreover, the epigenetic regulator CXXC5 and Tet2 are essential in the fight against viral infections." (PMID 33184433, 2020). "Collectively, these results demonstrated that SARS-CoV-2 infection led to increased RNA hydroxymethylation, and knockdown of TET2 may effectively suppress viral infection and N-protein expression, as well as inhibit the level of hm5C during SARS-CoV-2 infection." (PMID 40697650, 2025). "RJ-31, a 61-year-old patient, likely had a small T-cell clone carrying a TET2 mutation, which posed a hidden risk before being used for CAR-T manufacturing—leading to the uncontrolled expansion of CAR-T cells derived from autologous lymphocytes upon viral infection." (PMID 40547010, 2025). "Ten-eleven translocation 2 (TET2), a methylcytosine dioxygenase, plays key roles in DNA demethylation during viral infection and host–virus interactions." (PMID 40697650, 2025). "A small clone with TET2 mutation could conceal in RJ-31’s T lymphocytes before their collection for CAR-T preparation, constituting a risk of wild outgrowth of CAR-T cells derived from the autologous lymphocytes under certain circumstance, such as viral infection." (PMID 38191582, 2024). "While M1801 carried a TET2 mutation, whole-exome sequencing did not indicate significant abnormalities in the TET2 mutation across the four episodes of CRS, and viral infection was also present." (PMID 40547010, 2025). "Understanding TET2-driven epitranscriptomics and the functions of TET-targeting inhibitors may provide a novel strategy for mitigating viral infection in SARS-CoV-2-induced cardiomyopathy." (PMID 40697650, 2025). "HIV-1 Vpr and its Vpr/Vpx homologs in HIV-2 and SIV associate with the cullin4A-DDB1-DCAF1 complex to target multiple host factors including tet methylcytosine dioxygenase 2 (TET2) and helicase-like transcription factor (HLTF) for degradation, thus promoting virus infection." (PMID 31968566, 2020).
ovarian carcinoma (11 papers, 2017 to 2025). A malignant neoplasm originating from the surface ovarian epithelium. "All three members of the TET family are mutated in colon cancer, and TET2 mutations and deletion are also observed in clear cell renal cell carcinoma and ovarian carcinoma patients." (PMID 38003566, 2023). "Survival analysis between TET2 high expression and low expression groups in patients with ovarian cancer (Kaplan-Meier Plotter)." (PMID 35223782, 2022). "Furthermore, in metastatic cancers such as breast and ovarian cancer, low TET2 and 5hmC levels were positively correlated with the resistance of cancer cells to chemotherapeutic drugs such as PARP inhibitor olaparib and alkylating agent cisplatin." (PMID 38003566, 2023). "Moreover, pioneering studies employing retroviral transduction of Zinc-finger proteins engineered with TET-2-CD have shown reactivation of candidate TSGs, such as C13ORF18 and TFPI2 in cervical cancer cells, and ICAM-1 in ovarian cancer cells." (PMID 37120619, 2023).
peripheral T-cell lymphoma (11 papers, 2016 to 2025). "It is interesting to note that in peripheral T cell lymphomas, mutations in TET2 are common and TET2 loss promotes CD8+ T cell differentiation." (PMID 40274312, 2025). "DNMT 3A mutation is correlated with Ten-Eleven Translocation 2 (TET2) mutation in peripheral T-cell lymphoma (PTCL)." (PMID 35326620, 2022). "The identification of Ten eleven translocation -2 (TET2), Isocitrate Dehydrogenase (IDH) and DNA methyl transferase 3A (DNMT3A) mutations in peripheral T-cell lymphoma has been a major advance." (PMID 29966370, 2018). "Additionally, studies on cytotoxic peripheral T-cell lymphoma, not specifically focused on EBV+ cases, revealed frequent mutations in epigenetic modifiers, such as TET2, DNMT3A, and genes involved in the JAK/STAT pathway." (PMID 38921179, 2024).
Stroke (11 papers, 2013 to 2026). Sudden impairment of blood flow to a part of the brain due to occlusion or rupture of an artery to the brain. "By stroke subtypes, TET2 was strongly associated with small vessel stroke (SVS) (OR = 1.29, P = 0.01), weakly associated with large artery stroke (LAS) (OR = 1.21, P = 0.06), and not with cardioembolic stroke." (PMID 40093911, 2025). "After adjusting for age, sex, initial stroke severity, and ancestry, TET2 remained moderately associated with adverse functional outcomes (OR = 1.30, P = 0.02." (PMID 40093911, 2025). "A major future direction is to perform stroke models with primary TET2 deficient mice to validate the clinical and genetic findings in vivo." (PMID 40093911, 2025). "There were no heterogeneity and pleiotropy effects for the association between TET2 and adverse functional stroke outcome." (PMID 40093911, 2025). "Only TET2 was associated with a moderately increased risk for overall stroke (OR = 1.064, P = 0.021)." (PMID 40093911, 2025). "Collectively, we showed that TET2 not only increased the risk of ischemic stroke but also worsened the functional outcome after a stroke, highlighting its clinical significance as a prominent emerging risk factor for stroke occurrence and recovery." (PMID 40093911, 2025). "Third, the precise mechanisms by which TET2 drives stroke risk need further elucidation, specifically how different mutations within the TET2 gene may confer varying levels of risk through animal models." (PMID 40093911, 2025). "TET2 loss‐of‐function mutation may increase stroke risk and worsen outcomes through dysregulated hematopoietic cell function and chronic systemic inflammation." (PMID 40093911, 2025). "Additionally, we have independently replicated the main finding from two previous large‐scale cohort analyses on the association between TET2 and stroke." (PMID 40093911, 2025). "Tet methylcytosine dioxygenase 2 (TET2), a regulator of DNA methylation, is reduced in human aging and somatic mutations are associated with an elevated risk of developing age-related disorders such as stroke." (PMID 32848716, 2020). "These mutations, notably in genes like DNMT3A, TET2, and JAK2, induce pro-inflammatory and pro-atherosclerotic processes, promoting vascular damage and stroke risk." (PMID 39997650, 2025). "Peripheral blood was collected pre- and 14 d post-stroke or sham surgery in mice transplanted with either Tet2-KO or WT BM cells and analyzed for CD45.2 donor cell chimerism." (PMID 39742155, 2024). "This improved outcome is associated with lower levels of inflammation, perhaps indicative that Tet2-mutant leukocytes promote inflammation resolution after stroke, allowing for neurological recovery." (PMID 39742155, 2024). "Here we intentionally assessed the impact of Tet2-mediated CH on stroke outcome using a mouse model that is void of the confounding effects of underlying cardiovascular disease." (PMID 39742155, 2024). "Mice transplanted with Tet2-KO BM showed a significant improvement in their neurological deficit score from 3 to 14 d post-stroke, and their scores were significantly lower than mice transplanted with WT BM cells." (PMID 39742155, 2024). "Principal component analysis revealed that the response to stroke during subacute phase was different between mice transplanted with Tet2-KO and WT BM cells." (PMID 39742155, 2024). "To understand the potential mechanisms by which Tet2-mediated CH leads to a modestly improved functional outcome at 14 d post-stroke, we next examined its effects on inflammation during subacute phase of stroke." (PMID 39742155, 2024). "Moreover, Mendelian randomization (MR) analyses have revealed direct genetic causality between TET2‐CHIP and stroke risk." (PMID 40702735, 2025). "Despite the compelling evidence linking TET2 with stroke, several limitations remain in our study." (PMID 40093911, 2025).